PIGP (phosphatidylinositol glycan anchor biosynthesis class P)
Description:
Part of the glycosylphosphatidylinositol-N-acetylglucosaminyltransferase (GPI-GnT) complex that catalyzes the transfer of N-acetylglucosamine from UDP-N-acetylglucosamine to phosphatidylinositol and participates in the first step of GPI biosynthesis.
Synonyms: PIG-P; DCRC; DSCR5; DSRC; DCRC-S; DEE55; EIEE55
Tractability: Antibody: UniProt predicts a signal peptide or a membrane-spanning region. PROTAC: ubiquitination databases record sites on it.
Gene: Protein-coding gene on chromosome 21 (37,062,846 to 37,073,318, reverse strand). Ensembl gene ENSG00000185808.
Subcellular location: Membrane
Subcellular location (Human Protein Atlas): Vesicles
Pathways (Reactome):
Metabolism of proteins: Synthesis of glycosylphosphatidylinositol (GPI)
Gene Ontology:
Molecular function: phosphatidylinositol N-acetylglucosaminyltransferase activity; protein binding
Biological process: GPI anchor biosynthetic process
Cellular component: endoplasmic reticulum membrane; glycosylphosphatidylinositol-N-acetylglucosaminyltransferase (GPI-GnT) complex; endoplasmic reticulum; membrane
Genetic constraint (gnomAD): Loss-of-function variants: 13 observed, 8.34 expected, observed/expected ratio (o/e) 1.56, 90% interval 0.98 to 1.94. That is too few expected variants to judge how well the gene tolerates losing a copy. Missense variants: 77 observed, 81.07 expected, observed/expected ratio (o/e) 0.95, 90% interval 0.79 to 1.15. Synonymous variants: 29 observed, 29.14 expected, observed/expected ratio (o/e) 1, 90% interval 0.74 to 1.36.
Gene-disease validity (ClinGen):
ClinGen rates the evidence that PIGP causes each of these diseases.
developmental and epileptic encephalopathy, 55 (autosomal recessive): Moderate.
Homologues: Orthologues: chimpanzee PIGP (100% identical), macaque PIGP (98% identical), dog PIGP (95% identical), rabbit PIGP (93% identical), guinea pig Pigp (93% identical), pig PIGP (92% identical), rat Pigp (91% identical), mouse Pigp (90% identical), tropical clawed frog pigp (78% identical), zebrafish pigp (60% identical).
Diseases named in the same sentence as PIGP in open-access papers:
PIGP is named in the same sentence as 10 diseases in open-access papers, as found by Europe PMC text mining. Sharing a sentence is not in itself a finding about the gene and the disease. The quoted sentences say what the papers report.
Down syndrome (2 papers, 2016 to 2018). "PIGP regulates glycosylphosphatidylinositol-anchor biosynthesis in animals and has also been related to Down syndrome." (PMID 29883365, 2018). "Moreover, PIGP was found to be overexpressed in the fetal cortex brain of Down syndrome subjects." (PMID 26848775, 2016).
diverticulosis (1 paper, 2023). "In the MA GWAS for diverticulosis, rs2835676 (DSCR9 gene) showed strong eQTL association with both transverse and sigmoid colon tissues within the PIGP and TTC3 genes (FDR<3.90E-13)." (PMID 37196047, 2023).
Hypsarrhythmia (1 paper, 2020). Hypsarrhythmia is abnormal interictal high amplitude waves and a background of irregular spikes. "Additionally, hypsarrhythmia EEG was reported in IGDs caused by disease-causing variants in PIGA, PIGP, and PIGW." (PMID 32612635, 2020).
infantile epileptic encephalopathy (1 paper, 2019). an epileptic condition characterized by epileptiform abnormalities associated with progressive cerebral dysfunction. "Mutations in PtdIns glycan anchor biosynthesis (PIG) genes such as PIGP (MIM 617599) and PIGA (MIM 300868) can cause early infantile epileptic encephalopathy." (PMID 31413155, 2019).
PIGP also shares sentences with these, for which no sentence is quoted: genetic diseases (2 papers); autism spectrum disorder (1); carcinoma (1); keratitis (1); neurodevelopmental disorder (1); tumor (1).